VWF (von Willebrand factor)
Diseases named in the same sentence as VWF in open-access papers (continued):
Sharing a sentence is not in itself a finding about the gene and the disease.
COVID-19 (continued). "A particularly interesting issue regarding platelet function in COVID-19 patients concerns the role of vWF." (PMID 39795908, 2024). "Examples include proteins involved in coagulation (fibrinogen and VWF) whose levels were significantly reduced amongst COVID-19 convalescents." (PMID 38396092, 2024). "Similar to the processes of ARDS in COVID-19, there is an activation of vWF from damaged endothelial cells that stimulates platelet aggregation." (PMID 39334765, 2024). "Integrin αvβ3, an adhesion receptor for vWF, has emerged as a novel therapeutic target for treating sepsis and COVID-19 by lowering enhanced endothelial permeability." (PMID 38921594, 2024). "Proteomic analysis of COVID-19 EVs identified Von Willebrand factor and serum amyloid A-2 as among the most significant differentially expressed proteins across severity groups." (PMID 39475319, 2024). "Remarkably, the VWF has been observed elevated in COVID-19 patients, acting as a marker of acute and sustained EC activation and predictor of poor outcomes." (PMID 38378550, 2024). "In recovering COVID-19 patients, EC biomarkers such as von Willebrand factor (vWF) antigen, vWF pro peptide (vWFpp), and factor VIII (FVIII: C) are markedly elevated." (PMID 38337760, 2024). "ADAMTS13, a Disintegrin And Metalloproteinase with A Thrombospondin Motif 13, cleaves VWF multimers, and low levels have been shown in COVID-19 as well as other inflammatory conditions." (PMID 39237986, 2024). "VWF has been found to be elevated in COVID-19 patients, acting as a marker of acute and sustained endothelial cell activation and a predictor of poor outcomes." (PMID 39199353, 2024). "An elevated VWF (the marker for endothelial injury) level was also observed in COVID-19 patients in the ICU." (PMID 39199353, 2024). "Despite evidence indicating elevated IL-6 and VWF in COVID-19, and some data supporting the use of IL-6 as a prognostic indicator, especially for oxygen requirement, neither IL-6 nor VWF were indicative of progression to severe disease in our cohort." (PMID 39459948, 2024). "This study emphasizes the importance of understanding NET markers and vWF levels of COVID-19 patients with thrombotic events in order to better inform the prevention of future thrombotic events due to coagulopathy in COVID-19 and other related illnesses." (PMID 39599792, 2024). "Previous clinical studies have demonstrated that COVID-19 leads to an increase in vWF levels in patients, with implications suggesting a potential association with vascular endothelial cell damage." (PMID 38649864, 2024). "VWF and citH3 were also significant predictors of thrombotic events in all COVID-19 hospitalized females (p = 0.0305 and p = 0.0206, respectively)." (PMID 39599792, 2024). "A single-center, cross-sectional study from Yale–New Haven Hospital found a greatly increased amount of von Willebrand factor in COVID-19 patients." (PMID 38255892, 2024). "Whilst baseline VWF was significantly elevated in the three COVID-19 subgroups, sTM was significantly elevated in the moderate-severe and critical group." (PMID 38263377, 2024). "Building upon these findings, the present study revealed a similar upregulation of vWF in CKD patients affected by COVID-19, indicating a link between the hypercoagulable state in these individuals and vWF." (PMID 38649864, 2024). "Incubation of plasma from acute COVID-19 patients with EC triggered VWF secretion and Angpt-2 expression, as well as EC tube formation and angiogenesis." (PMID 38378550, 2024). "COVID-19 patients demonstrate significantly elevated levels of antigen and vWF activity, as well as ADAMTS-13 activity." (PMID 39795908, 2024). "Patients with COVID-19 have elevated procoagulant factors including Von Willebrand Factor (VWF) and factor VIII, secondary to direct endothelial activation, with higher levels associated with increased severity of disease." (PMID 39043682, 2024).
COVID-19 (continued). "The significantly decreased levels of VWF and fibrinogens in COVID-19 convalescents contrasts the finding that most components of the coagulation and complement cascade had returned to pre-infection levels." (PMID 38396092, 2024). "Reports indicate that COVID-19 patients exhibit significantly higher vWF activity and concentration compared to normal controls, and that vWF is a procoagulant factor." (PMID 38214889, 2024). "As increased vWF levels are a reliable predictor of future venous and arterial thromboembolic events, levels of vWF and NETs could serve as potential biomarkers of risk for COVID-19-related thrombosis and allow for improved monitoring of future thrombotic event risk." (PMID 39599792, 2024). "Specifically, two proteins released by activated endothelial cells (EC), namely the von Willebrand Factor (vWF) antigen and soluble P-selectin, are significantly elevated in patients with COVID-19." (PMID 38771750, 2024). "We demonstrate that levels of factor VIII and VWF antigen are elevated in acute COVID-19, and can be safely and effectively be reduced by PEX." (PMID 39043682, 2024). "Significant dysregulation of the coagulation cascade is observed in critically ill patients with COVID-19, including elevated D-dimer, fibrinogen, and von Willebrand factor." (PMID 38348024, 2024). "Binding of VWF was impaired in 12 of 13 COVID-19 patients after incubation with higher ristocetin concentrations (0.5–1 mg/mL)." (PMID 36611985, 2023). "This is in line with the growing clinical evidence that increased plasma VWF levels correlate with COVID-19 mortality and the recent evidence that additionally imply an instrumental role of VWF in post–COVID-19 complications." (PMID 37333991, 2023). "Blood coagulation parameters including the von Willebrand factor (vWF) activity and antigen showed a significant elevation in the COVID-19 group (p < 0.01 for both parameters)." (PMID 37386635, 2023). "COVID-19 patients demonstrate significantly elevated levels of antigen and activity of vWF and mildly to moderately-reduced ADAMTS-13 activity." (PMID 36982387, 2023). "In plasma samples from patients with COVID-19, von Willebrand factor (VWF) levels are highly elevated and predictive of adverse outcomes, especially mortality." (PMID 37333991, 2023). "Compared to healthy controls VWF:Ag (iU/mL) was significantly higher in patients with COVID-19 (326 iU/mL, interquartile range (IQR) 163 vs. 97 iU/mL, IQR 61, p<0.0001)." (PMID 37380654, 2023). "We performed plasma exchange in 25 critically ill COVID-19 patients with acute respiratory distress syndrome, leading to a significant decrease in VWF:Ag and increased ADAMTS13 activity." (PMID 37380654, 2023). "These alterations are consistent with the observation that the majority of our COVID-19 patients had high plasma levels of VWF, a reliable marker of endothelial involvement, and these levels were significantly correlated with the number of enlarged loops." (PMID 37297922, 2023). "The thromboembolic complications of COVID-19 can be monitored by comparing the elevated levels of D-dimers, the fibrinogen, and the vWF with the normal ranges of PT, aPTT, and platelet count." (PMID 38188630, 2023). "In the late stages of COVID-19, the lab indices of the patients revealed an increase in von Willebrand factor (vWF) and factor VIIIC, both of which are important classic markers of coagulability." (PMID 37873794, 2023). "In this study, we performed analyses of platelet function and of von Willebrand factor in critically ill COVID-19 patients (n = 13)." (PMID 36611985, 2023). "A meta-analysis showed that higher plasma levels of vWf antigen, tPA, PAI-1, and sTM were associated with composite poor outcome in COVID-19 patients." (PMID 37175942, 2023). "•Plasma levels of von Willebrand factor, angiopoietin-2, osteoprotegerin, and soluble thrombomodulin are elevated in patients with severe COVID-19." (PMID 36817284, 2023).
COVID-19 (continued). "A study investigating markers of endothelial injury in COVID-19 ICU patients compared with inpatient controls demonstrated that VWF and P-selectin were significantly elevated in severe COVID-19, suggesting endothelial damage as a driver of coagulopathy." (PMID 37159776, 2023). "Various studies reported that, in severe COVID-19, vWF levels tend to be elevated, accompanied by decreased ADAMTS13 levels." (PMID 38069327, 2023). "The principal molecules stored and rapidly released from Weibel–Palade bodies by exocytosis are vWf, Ang-2, and P-selectin, all of which are elevated in critically ill COVID-19 patients, implying early dysregulation of haemostasis and inflammation." (PMID 37175942, 2023). "Incubation of COVID-19 plasma with ECs triggered enhanced VWF secretion and increased Angpt-2 expression, as well as significantly enhanced in vitro EC tube formation and angiogenesis." (PMID 36817284, 2023). "Serum vWF levels at the time of hospital admission correlates with different grades of COVID-19 severity (mild, moderate and severe/critical; n = 333), and with increased risk of mortality during hospital stay." (PMID 36941580, 2023). "The potential mechanism of the increased platelet-vWF interactions observed in COVID-19 patients or in vitro is difficult to explain." (PMID 36982387, 2023). "Of note, the GP1b-IX-V complex is a platelet receptor that mediates the initial interaction with subendothelial vWF which levels were elevated in COVID-19 patients." (PMID 36943669, 2023). "High levels of vWF are related to the severity of respiratory diseases such as COVID-19, which attests to its potential as a marker of endothelial cell activation and inflammation." (PMID 37958192, 2023). "Platelet adhesion and thrombus formation are among the most prominent features of COVID-19, as demonstrated by increased fibrinogen, and various markers of endothelial cell and platelet activation, including vWf, sTM, sCD40L, PAI-1, and sP-selectin." (PMID 37175942, 2023). "Markedly elevated plasma VWF antigen, Angpt-2, osteoprotegerin, and sTM levels were observed in patients with acute COVID-19." (PMID 36817284, 2023). "In summary, the present findings show that the higher VWF concentrations and the lower ADAMTS13, the higher the probability of a severe course of COVID-19 including risk of death." (PMID 37380654, 2023). "Our current findings are in agreement with clinical data showing that COVID-19 patients have significantly increased levels of circulating P-selectin, vWF antigen, and F-VIII activity." (PMID 37628764, 2023). "Of particular interest is extensive damage to endothelial cells in severe COVID-19 patients, with an associated presence of SARS-CoV-2 virus and SP and elevated levels of VWF." (PMID 38069362, 2023). "Another study showed that serum vWF levels in severe COVID-19 patients admitted to ICU (n = 28) tended to increase during the first days of hospitalization and to then decrease after the acute phase, until 3 months of convalescence following ICU discharge." (PMID 36941580, 2023). "Autopsy results of patients with severe COVID-19 have shown the occurrence of severe capillary congestion, in part by microthrombi, some of which exhibit vWF positivity." (PMID 36768817, 2023). "It is important to bear in mind, however, that most of the studies conducted on vWF as a biomarker for ARDS have focused on COVID-19, and additional research is needed to assess its significance in other etiologies of ARDS." (PMID 37958192, 2023). "The increased levels of both sTM and Weibel-Palade body components (VWF, osteoprotegerin, and Angpt-2) correlated with COVID-19 severity." (PMID 36817284, 2023). "A markedly different pattern was observed with vWF, with levels significantly elevated in all COVID-19 patients compared to controls." (PMID 37448794, 2023).
COVID-19 (continued). "A previous study demonstrated that a majority of COVID-19 patients had coagulation aberrations that manifested as high levels of D-dimers, fibrinogen and von Willebrand factor (vWF), prolonged prothrombin time and low platelet number." (PMID 37251383, 2023). "Levels of vWF factor are severely elevated in COVID-19 patients, even in hospitalized patients with relatively moderate symptoms." (PMID 37526812, 2023). "A case report reported increased plasma antigen and vWF activity as well as an increased FVIII activity level on day 21 of hospitalization in a critically ill COVID-19 patient, indicating endothelial cell injury." (PMID 37092518, 2023). "In the myocardium, VWF+ microthrombi were found in 50% of the patients with COVID-19 but also in 44% of the controls." (PMID 37333991, 2023). "For prediction severity of COVID-19, ATIII has higher diagnostic accuracy (62.3%) in comparison to VWF (52.3%) and LA-1 (59%)." (PMID 36138306, 2023). "Since vWF levels also increase in COVID-19 patient blood and endothelial cells are known to secrete vWF, we also analyzed the time-dependent effect of the RBD treatment on vWF secretion from the EA.hy 296 cell monolayer." (PMID 36982738, 2023). "Within pulmonary draining lymph nodes, VWF thrombi seemed more commonly observable in the patients with COVID-19 than in the controls, and the overall presence of VWF within lymph nodes was very high, which has similarly been shown on a transcriptional level." (PMID 37333991, 2023). "In agreement with previous findings, the Von Willebrand factor (VWF) was upregulated in patients with COVID-19 which can contribute to their hypercoagulable state and increased venous thromboembolism rate." (PMID 37047248, 2023). "It has been shown that COVID-19 patients present with elevated levels of soluble thrombomodulin, von Willebrand Factor (VWF), and proinflammatory IL-6, all indicative of procoagulant endothelial phenotype, i.e., endotheliopathy." (PMID 36634048, 2023). "In this study, we evaluated the in situ distribution of VWF in human tissues (lungs, pulmonary draining lymph nodes, and hearts) in a COVID-19 autopsy cohort in comparison with that in matched controls with analogous sequelae." (PMID 37333991, 2023). "One of the key findings of this study was that immunostaining analysis indicated that LSECs in COVID-19 patients were highly positive for vWF and demonstrated platelet recruitment at their surface." (PMID 37376587, 2023). "We compared autopsy samples from 28 patients with lethal COVID-19 to those from matched controls and systematically assessed for VWF and platelets by immunohistochemistry." (PMID 37333991, 2023). "In previous studies, we confirmed that COVID-19 patients exhibited significantly elevated levels of vWF in their plasma samples, which was directly correlated with the severity of the disease." (PMID 38139298, 2023). "Interaction between platelets, VWF, NETs and inflammasomes is critical for the progression of thromboinflammation in several diseases and was recently shown to be active in COVID-19." (PMID 38203218, 2023). "In all COVID-19 patients, VWF:Ag was substantially higher than the normal range (474 ± 144%, mean ± SD)." (PMID 36611985, 2023). "Given the severe endothelial damage and hyperinflammation in patients with COVID-19 and the physiologic functions of VWF, it is conceivable that VWF plays a role in thrombosis in COVID-19." (PMID 37333991, 2023). "We observed that all participants and patients with moderate COVID-19 showed higher vWF activity as AOPP levels increased." (PMID 37554121, 2023). "Hypercoagulation among COVID-19 patients involves increased blood levels of fibrinogen, thrombin, thrombin-anti-thrombin complex, activated platelets, von Willebrand factor (vWF), and circulating endothelial cells." (PMID 38143504, 2023). "•When autopsy samples were compared with matched controls, VWF-rich thrombi were more frequent in samples from patients with COVID-19." (PMID 37333991, 2023).
COVID-19 (continued). "The authors showed increased expression of von Willebrand factor in placental endothelium (decidua and villi) and decreased claudin-5 and vascular endothelial cadherin in women with severe COVID-19." (PMID 37760899, 2023). "There were moderate correlations between levels of AOPP and vWF (r = 0.4238), and creatinine (r = 0.4163) in the group of moderate COVID-19 patients." (PMID 37554121, 2023). "The ADAMTS13/VWF:Ag ratio was substantially lower in COVID-19 patients (20.2±9.4 vs. 82.0±30.7, p<0.0001)." (PMID 37380654, 2023). "A larger study of 203 COVID-19 patients found that over 80% had raised vWF levels 3 months after the onset of infection." (PMID 37448794, 2023). "SARS-CoV-2 was detected using reverse transcription-PCR in 85% of lung samples in the COVID-19 cohort, and in all but 1 case (91%) in which VWF+ microthrombi were found." (PMID 37333991, 2023). "In CAEC exposed to the post-COVID-19 serum, the synthesis of vWF increased by 22%, p < 0.01, as compared to the control serum." (PMID 38188630, 2023). "In COVID-19 samples, mononuclear cells in the paracortical zones of the lymph nodes frequently displayed positive staining for VWF (40% of COVID-19 cases showed >5% VWF+ histiocytes vs 21% of controls; P = .038)." (PMID 37333991, 2023). "The lung autopsies of COVID-19 patients suggest increased vWF expression not only from ECs, but also by activated platelets, as it was detected in the outer layer of the thrombus and CD31-expressing vascular endothelium tissue samples." (PMID 36979908, 2023). "In a separate hospitalized group, E-selectin levels were raised in severe disease only, but Von Willebrand factor was raised in all patient groups with COVID-19." (PMID 37448794, 2023). "Dyshemostasis characterized COVID-19, with increased prothrombin time, low platelet count, and high levels of interleukin 6, fibrinogens, and von Willebrand factor, among other abnormalities." (PMID 36527584, 2023). "It is also known that mice exposed to hypoxia demonstrated an increase in VWF expression accompanied by the occurrence of thrombi in the heart and lungs, similar to COVID-19." (PMID 37175037, 2023). "Both VWF and A2 are markedly elevated in patients severely ill with COVID-19 and are predictive of mortality." (PMID 37189034, 2023). "A set of single nucleotide polymorphisms (SNPs) in the vWF (rs216311, rs216321, rs1063856, rs1800378, rs1800383) and ADAMTS13 genes (rs2301612, rs28729234, rs34024143) were genotyped in 72 COVID-19 patients." (PMID 36980889, 2023). "It is known that COVID-19 patients experienced significantly increased levels and function of vWF together with increased FVIII clotting activity, while ADAMTS13 activity slightly decreased." (PMID 37092518, 2023). "Platelet activation is a major driver of inflammation/thrombogenesis, and von Willebrand factor (vWF) and Platelet Factor 4 (PF4) are deeply involved in the pathogenesis of COVID-19-associated coagulopathy." (PMID 37189799, 2023). "When comparing COVID-19 cases to healthy controls, significant differences were observed in the von Willebrand factor (vWF) and factor XIII levels." (PMID 36829233, 2023). "In patients with severe COVID-19, IL-10 was negatively correlated with vWF, which indicated endothelium dysfunction." (PMID 37814134, 2023). "Furthermore, the loss of the endothelial glycocalyx in COVID-19 patients may facilitate platelet adhesion, the infiltration of inflammatory cells into the vessel wall, and the release of endothelial products such as von Willebrand factor into the circulation." (PMID 35323682, 2022). "The results of the study demonstrated an important role of endothelial VWF in the pathogenesis of thrombus formation in COVID-19." (PMID 35215805, 2022). "Since bacterial pneumonia and lung ventilation are independent predictors of increased IHC reaction for VWF, more focus should be placed on the role of lung ventilation and superinfection in the pathogenesis of thrombus formation in COVID-19." (PMID 35215805, 2022).